FBXW10 (F-box and WD repeat domain containing 10)
Description:
Probable substrate-recognition component of a SCF (SKP1-CUL1-F-box protein)-type E3 ubiquitin ligase complex which mediates the ubiquitination and subsequent proteasomal degradation of target proteins. Overexpression is leading to degradation of CBX5 and CBX1.
Synonyms: SM2SH2; HREP; Fbw10; SM25H2; formerly C17orf1; C17orf1A
Tractability: No criterion of Open Targets' tractability assessment is met for any kind of drug.
Gene: Protein-coding gene on chromosome 17 (18,744,026 to 18,779,349, forward strand). Ensembl gene ENSG00000171931.
Subcellular location (Human Protein Atlas): Nucleoplasm
Pathways (Reactome):
Metabolism of proteins: Association of TriC/CCT with target proteins during biosynthesis; Neddylation
Immune System: Antigen processing: Ubiquitination & Proteasome degradation
Gene Ontology:
Biological process: SCF-dependent proteasomal ubiquitin-dependent protein catabolic process
Cellular component: cytosol; SCF ubiquitin ligase complex
Genetic constraint (gnomAD): Loss-of-function variants: 61 observed, 100.56 expected, observed/expected ratio (o/e) 0.61, 90% interval 0.49 to 0.75. The synonymous counts are far from expectation, so gnomAD's model fits this gene poorly and the ratio says little. Missense variants: 732 observed, 1,161.6 expected, observed/expected ratio (o/e) 0.63, 90% interval 0.59 to 0.67. Synonymous variants: 279 observed, 428.81 expected, observed/expected ratio (o/e) 0.65, 90% interval 0.59 to 0.72.
Homologues: Orthologues: macaque FBXW10B (94% identical), dog FBXW10B (78% identical), mouse Fbxw10 (69% identical), rat Fbxw10 (68% identical), tropical clawed frog cdrt1 (38% identical), zebrafish fbxw10 (21% identical). Paralogues in human: FBXW10B (66% identical).
Diseases named in the same sentence as FBXW10 in open-access papers:
FBXW10 is named in the same sentence as 5 diseases in open-access papers, as found by Europe PMC text mining. Sharing a sentence is not in itself a finding about the gene and the disease. The quoted sentences say what the papers report.
clear cell renal cell carcinoma (1 paper, 2017). "For instance, FBXW10 gene is found to be hypermethylated in clear cell renal cell carcinoma, while FBXO3 influences TGF‐β signaling by targeting SMURF1 for proteasomal degradation." (PMID 28397399, 2017).
gastric cancer (1 paper, 2025). A primary or metastatic malignant neoplasm involving the stomach. "First, we confirmed that FBXW10 can form a complex with ANXA2 and mediate K63 ubiquitination of ANXA2 in gastric cancer." (PMID 41185558, 2025).
hepatocellular carcinoma (1 paper, 2022). A malignant tumor that arises from hepatocytes. "High expression of FBXW10 is linked to poor survival in male hepatocellular carcinoma patients." (PMID 35909123, 2022).
thyroid disorders (1 paper, 2023). "PPI analysis could not link FBXW10 or SLC47A1 genes to a pathway that contributes to thyroid disorders or malignancies." (PMID 37175943, 2023).
cancer (1 paper, 2022). A tumor composed of atypical neoplastic, often pleomorphic cells that invade other tissues. "we further investigated that FBXW5 was highly expressed, FBXW10 and FBXW12 were lowly expressed, and other members were moderately expressed in pan-cancer." (PMID 36591289, 2022). "We further explored that the higher expression of FBXW10 in several cancers including LUAD, LUSC, LIHC, PRAD and STAD compared with normal tissues." (PMID 36591289, 2022).